TREM1 (triggering receptor expressed on myeloid cells 1)
Diseases named in the same sentence as TREM1 in open-access papers (continued):
Sharing a sentence is not in itself a finding about the gene and the disease.
lung carcinoma (continued). "Recent studies suggest that expression of TREM-1 in tumors may predict cancer aggressiveness and disease outcomes in liver and lung cancer implicating that expression of TREM-1 in macrophages may be a associated with tumor growth and progression." (PMID 24842612, 2014). "Furthermore treatment with COX-2 inhibitors and knockdown of COX-2 in macrophages attenuated the expression of TREM-1 in a co-culture model of lung cancer cells with macrophages." (PMID 24842612, 2014). "Recent studies suggest that expression of TREM-1 in tumors may predict cancer aggressiveness and disease outcomes in liver and lung cancer however the mechanism of TREM-1 expression in the setting of cancer is not defined." (PMID 24842612, 2014). "However, blockade of TREM-1 suppressed tumor growth in a human lung cancer xenograft model." (PMID 31275318, 2019). "Furthermore, TREM1 has been reported to be expressed in lung cancer epithelial cells." (PMID 28969663, 2017). "The low expression level of TREM-1 might be a characteristic for TAMs in lung cancer." (PMID 27244892, 2016). "In addition we also determined if lung cancer cells (A549 cells) express TREM-1 protein." (PMID 24842612, 2014). "The expression of TREM1 and proinflammatory cytokine (TNF, IL-1β) were upregulated in blood monocytes cocultured with lung cancer cells from patients with NSCLC." (PMID 37651197, 2023). "Studies assessing TREM-1 and/or soluble TREM-1 (sTREM-1) expression in human lung cancer and the correlation with survival data." (PMID 35875168, 2022). "To reveal the biological functions of TREM-1 in tumor microenvironment, we then sorted TAM from lung cancer tissues by flow cytometry." (PMID 27244892, 2016). "Another study used the protein named triggering receptor expressed on myeloid cells-1 (TREM-1) as a marker for TAMs and reported that TREM-1 was expressed only by CD68+ TAMs in lung cancer tissue." (PMID 27144518, 2016). "TREM-1 level is an independent predicator of survival in NSCLC, and might be a component of human lung cancer progression." (PMID 35875168, 2022). "It suggested that TREM-1 expression in lung tissue is not specific to infectious disease such as pulmonary TB, and is probably also involved in immunomodulation of lung cancer." (PMID 29844416, 2018). "Currently in lung cancer, there are no published studies which investigated how TREM-1 positive TAMs are polarized." (PMID 30018308, 2018). "In addition, analysis of the TREM1+ PMN-MDSCs population revealed that TREM1 exhibited high expression in multiple cancers, including renal cell carcinoma (RCC), pancreatic ductal adenocarcinoma (PDAC), gastric cancer (GC) and lung cancers (LC)." (PMID 41413734, 2025). "Moreover, TREM-1 was expressed in squamous metaplasia of cervicitis and lung cancer, while normal cervical SE and tongue carcinoma did not express TREM-1." (PMID 27409178, 2016). "The TREM-1 levels on monocytes/macrophages gradually reduced with the advance of tumor stage and lymph node metastasis, suggesting that TREM-1low on TAM might be a novel characteristic for advanced stage of lung cancer." (PMID 27244892, 2016). "Authors demonstrated that TREM-1 rates on monocytes/macrophages progressively decreased with the advancement of tumor stage and tumor invasion of lymph nodes, which suggests that weak TREM-1 expression on TAMs could be a new feature of advanced lung cancer stage." (PMID 35875168, 2022). "In lung cancer, TREM-1 is not expressed by cancer cells, but cancer cells induce the expression of TREM-1 in macrophages." (PMID 30018308, 2018).
myocardial infarction (22 papers, 2016 to 2025). Gross necrosis of the myocardium, as a result of interruption of the blood supply to the area, as in coronary thrombosis. "A follow-up study can focus on the dynamic expression profile of TREM1 after myocardial infarction, to provide a theoretical basis for TREM1 to participate in myocardial infarction risk stratification." (PMID 34221733, 2021). "TREM1 was related to these markers associated with adverse outcome of cardiac diseases, so we hypothesized that TREM1 may also be associated with the prognosis of myocardial infarction, which was also confirmed by the follow-up results." (PMID 34221733, 2021). "Patients who experienced a heart attack alone had lower serum TREM-1 levels than those who had both diabetes and a heart attack." (PMID 41451290, 2025). "Another study indicated that Sirt6-induced autophagy restricted TREM-1-mediated pyroptosis, which renders Sirt6 and TREM-1 inflammatory markers for use in prognosis stratification of acute myocardial infarction." (PMID 38172884, 2024). "The plasma expression level of soluble TREM1 has been considered one of the predictors of mortality in patients with acute myocardial infarction." (PMID 35722091, 2022). "In conclusion, using bioinformatics and after verification using plasma samples of patients with AMI, we found TREM1 is an important biomarker in myocardial infarction." (PMID 34221733, 2021). "TREM-1 was also found to amplify the inflammation following myocardial infarction, and its modulation provides a better outcome for post-AMI in both the short and long term." (PMID 30205488, 2018). "Furthermore, increased expression of TREM-1 has been observed in sterile conditions such as autoimmune diseases, ischemia-reperfusion injury, myocardial infarction, and acute kidney injury." (PMID 37168858, 2023). "TREM1 also played a crucial role in myocardial infarction (MI) by inducing excessive inflammatory responses and triggering cardiac dysfunction." (PMID 38333413, 2024). "Thus, TREM1 may play an important role in both acute myocardial infarction and diabetes progression." (PMID 34221733, 2021). "Second, this study only detected the expression level of TREM1 in the plasma of patients with AMI on admission, but did not dynamically monitor the changes of TREM1 one week after myocardial infarction." (PMID 34221733, 2021).
ischemic stroke (21 papers, 2014 to 2025). A stroke disorder caused by obstruction of blood flow to the brain, due to thrombotic (local blood clot formation) or embolic (due to a blood clot or other material traveling from another site) event. "In ischaemic stroke and subarachnoid haemorrhage, inhibition of TREM-1 is accompanied by decreased microglia-associated neuroinflammation." (PMID 38177990, 2024). "Although the specific nature of putative ligands for TREM-1 remains elusive, various pathological conditions, such as bacterial and fungal infections, and ischemic stroke, have been shown to induce its expression." (PMID 41226426, 2025). "Triggering receptor expressed on myeloid cells-1 (TREM-1) was reported to be critical for mediating the neurological function after stroke, while the impact of soluble TREM-1 (sTREM-1) on cognitive impairment after ischemic stroke is unclear." (PMID 39649719, 2024). "This study provides insights into the potential pathway of TREM-1 and TREM-2 as a future biomarker for stratifying high-risk patients with ischemic stroke." (PMID 39062850, 2024). "The triggering receptor expressed on myeloid cells 1 (TREM-1) is a surface molecule on macrophages and microglia that increases pro-inflammatory mediator secretion and release in ischemic stroke." (PMID 37915409, 2023). "In contrast, TREM1 mediates neuroinflammation in ischemic stroke by interacting with the SYK signaling pathway to activate downstream NF‐κB and NLRP3 inflammasome." (PMID 38680509, 2023). "In contrast, TREM1 mediates neuroinflammation during an ischemic stroke by interacting with the spleen tyrosine kinase (SYK) signaling pathway and activating downstream nuclear factor kappaB (NF‐κB) and NLRP3 inflammasome." (PMID 38680509, 2023). "Our data showed a significant decrease in peripheral Trem1+ myeloid cell differentiation after DNT cell treatment as early as 24 h after ischemic stroke." (PMID 36793857, 2023). "In recent years, many studies have found that TREM-1 expressed on microglia is involved in the pathological processes of CNS diseases, including ischemic stroke, SAH, cerebral hemorrhage, glioma, PD, AD, CNS infections, SCI and SCIRI." (PMID 36273145, 2022). "A study has shown that blockade of TREM-1 potentiates cellular proliferation in an experimental model of ischemic stroke, resulting in functional improvement." (PMID 34135689, 2021). "In experimental ischemic stroke and subarachnoid hemorrhage, microglial TREM-1 expression was upregulated, following cerebral ischemic or hemorrhagic injury, which exacerbates neuroinflammatory damage." (PMID 33375339, 2020). "We found that the serum levels of TREM-1 and NIHSS were significantly associated with predictive factors of functional outcomes in patients with ischemic stroke." (PMID 33375339, 2020). "To confirm the biological function of TREM-1 in ischemic stroke, we employed intranasal delivery of an inhibitory peptide called LP17 to block TREM-1 expression." (PMID 31324751, 2019). "Altogether, our data pointed to TREM-1 as a potential therapeutic target for treating ischemic stroke." (PMID 31324751, 2019). "Overall, these data suggested that blockade of TREM-1 rescues long-term neurobehavioral impairment through promoting cell proliferation and synaptic plasticity in hippocampus following ischemic stroke." (PMID 31324751, 2019). "Ischemic stroke or cerebral ischemia: TREM-1 also plays a significant role in cerebral ischemia." (PMID 41226426, 2025). "While TREM-1 has also been observed in microglia under certain pathological conditions, such as ischemic stroke, our findings underscore that, in the context of Parkinson’s disease-related neuroinflammation, the predominant contribution of TREM-1 arises from infiltrating monocytes." (PMID 39809747, 2025). "Studies have focused on TREM1/2 in the acute phase of ischemic stroke; what role TREM1/2 fills in the chronic phase is largely unknown, which is a direction for future research." (PMID 38385036, 2024).
ischemic stroke (continued). "Considering that TREM-1 exerts a detrimental effect on neurological function after ischemic stroke, there might be a potential correlation between circulating sTREM-1 levels and PSCI." (PMID 39649719, 2024). "A number of interconnected pathways previously associated with ischemic stroke were over-represented in females, including TLR (Toll-like receptor), HMGB1, TREM1, PPARα/RXRα, Hypoxia, Renin-Angiotensin, Mitochondrial Dysfunction, Glucocorticoid receptor and cytokine signaling pathways." (PMID 25036109, 2014). "Inhibition of TREM-1 not only ameliorates ischemia-induced neural damage but also promotes cell proliferation in the hippocampal region, enhances synaptic plasticity, and improves long-term neurobehavioural function in mice, providing a new direction for the treatment of ischemic stroke." (PMID 36273145, 2022). "Inhibiting TREM-1 with synthetic peptides like LP17 has been shown to reduce neuronal damage, enhance hippocampal synaptic plasticity, decrease infarct size, reduce BBB leakage, and improve functional recovery in ischemic stroke models." (PMID 41226426, 2025). "TREM-1 (Triggering Receptor Expressed on Myeloid Cells-1) and TREM-2 (Triggering Receptor Expressed on Myeloid Cells-2), as members of the TREM family, have been increasingly recognized for their roles in the inflammatory response and prognostic evaluation of ischemic stroke." (PMID 40869247, 2025).
viral infections (19 papers, 2013 to 2025). "TREM1 is a surface marker of neutrophils and monocytes that is activated during viral infections and a recent report identified that upregulation of TREM1 in peripheral blood is associated with decreased asthma control." (PMID 29486764, 2018). "The function of TREM-1 in modulating virus-associated inflammation appears to be supported more by in vitro studies using viral PAMPs, than actual virus infections." (PMID 25505454, 2014). "Comprehensive analysis of virus infections in vitro as well as in TREM-1 deficient mice will be required before we fully understand the cooperation between TREM-1 and other viral PRRs in the context of the virus-associated inflammation." (PMID 25505454, 2014). "We thus describe a previously unanticipated pathogenic role for TREM-1 also during a parasitic and viral infection." (PMID 24453980, 2014). "TREM-1 seems to be associated with the early stages of RV infection, with its expression decreasing throughout time, which is in accordance with previous studies conducted on viral infections (dengue and Crimean–Congo hemorrhagic fever)." (PMID 41156639, 2025). "A deeper conceptual understanding of the mechanisms associated with pathogenic and/or protective functions of TREM-1 in antiviral immunity is essential to develop novel therapeutic strategies for the control of virus infection by modulating innate immune signaling." (PMID 25505454, 2014). "However, a deeper conceptual understanding of the mechanisms associated with the pathogenic and protective functions of TREM-1 in antiviral immunity is essential to develop novel therapeutic strategies for controlling virus infection by modulating innate immune signaling." (PMID 34887856, 2021). "Thus far, however, it is unclear whether TREM1 activation is a common event in viral infections and whether TREM1 activity can modulate virus-associated inflammation." (PMID 27328755, 2016). "Despite the well-documentedrole of TREM-1 in different viral infections,its contribution to the NoV infection remains to be elucidated." (PMID 39959083, 2025). "As it has already been observed that Trem1 expression increases in different viral infections,we sought to investigate transcriptomic public data sets regardingTREM-1 in experimental MNoV infection." (PMID 39959083, 2025). "DDX58 can initiate an immune response to resist viral infections, while TREM1 can enhance non‐specific immune responses, which means they are valuable targets in future immunotherapy research." (PMID 38425247, 2024). "To date, TREM-1 modulation in viral infections has been described for dengue, Marburg (MARV), Ebola (EBOV) and human immunodeficiency (HIV) viruses among others." (PMID 32123257, 2020). "Although TREM1 activity was initially described only in the context of bacterial or fungal infections, a role for TREM1 during viral infections is emerging." (PMID 31719184, 2019). "TREM-1 is known to be an immune regulator against viral infection, septic shock, pneumonia, and asthma." (PMID 31275318, 2019). "Studies focusing on other distinct viruses have also demonstrated that viral infection results in upregulation of TREM1 and that expression can be organ specific." (PMID 31260499, 2019). "Although the data on the functions of TREM-1 in virus infections is limited, in vitro studies using viral PAMPs suggest the ability of viruses to modulate TREM signaling." (PMID 25505454, 2014). "The TREM1 and IL-17 pathways are both pro-inflammatory and have been shown to play significant and complex roles in the control of both bacterial and viral infections." (PMID 24073225, 2013). "Additionally, our results strongly suggesta direct role for TREM-1 in NoV pathogenesis, as well as its potentialfunction as a coreceptor during this viral infection." (PMID 39959083, 2025). "Thus, the upstream regulators involved in viral infection are likely to utilize the TREM-1 signaling pathway to mediate inflammatory responses in EV-D68 infection." (PMID 34887856, 2021).
viral infections (continued). "Therefore, inhibition of TREM-1 specifically targeted the downstream immune response after virus infection." (PMID 32123257, 2020). "TREM1 is exclusively expressed in the myeloid cell lineage and is involved in the amplification of production of inflammatory cytokines and chemokines during viral infection." (PMID 31260499, 2019). "Their study implies that limiting inflammation by blocking TREM-1 in the setting of acute viral infection may contribute to its protective effect." (PMID 28181540, 2017). "Most studies have focused on non-viral infections, but recent studies have shown that TREM-1 signaling may also play a critical role in viral innate adaptive response." (PMID 28181540, 2017). "At this point, one can only speculate the role of sTREM in pathogenesis of DENV, an important global human pathogen, however, this is an important finding and provides direct evidence of modulation of TREM-1 in response to virus infection." (PMID 25505454, 2014). "Thus, it is conceivable that viral hepatitis might well be suited for clarifying the putative role of TREM1 in viral infections." (PMID 27328755, 2016). "Although the role of TREM-1 has been little studied in viral infections so far, studies demonstrate increased gene expression of the TREM1 during viral infections in vitro, suggesting activation of TREM-1 signaling by viruses." (PMID 36859461, 2023). "However, it is not yet established whether activation of TREM-1 is pathogenic or protective in viral infections." (PMID 34887856, 2021). "With regard to viral infections, West Nile virus (WNV) increases TREM1 expression in murine macrophages and dendritic cells and enhances TREM1 signaling in murine livers." (PMID 31719184, 2019). "Therefore, interference with the functions of TREM1 or neutrophils may be a therapeutic target enabling the treatment of viral infection-associated immunopathologies without affecting viral clearance." (PMID 27328755, 2016). "Also, we performed ELISA experiments to characterize the change in levels of TREM-1 downstream cytokines, and the results proved that IL-6, IL-8, TNF-α, and others were indeed upregulated in response to viral infection." (PMID 34887856, 2021). "After having established that deficiency in TREM-1 attenuates disease but does not impair pathogen control during a parasitic and viral infection, we last sought to address the significance of TREM-1 in a bacterial infection model." (PMID 24453980, 2014). "However, characterization of several additional roles of TREM-1 such as modulation of T-cell proliferation and APC activation clearly argues for its crucial immunomodulatory role in virus infections." (PMID 25505454, 2014). "In summary, while the impact of TREM-1 on microbial control still needs further investigations across different experimental models, our extensive characterisation of Trem1−/− mice shows an unanticipated prominent role for TREM-1 in parasitic and viral infections." (PMID 24453980, 2014).